DUSP16 (dual specificity phosphatase 16)
Description:
Dual specificity protein phosphatase involved in the inactivation of MAP kinases. Dephosphorylates MAPK10 bound to ARRB2.
Synonyms: MKP-7; KIAA1700; MKP7
Tractability: PROTAC: ubiquitination databases record sites on it.
Gene: Protein-coding gene on chromosome 12 (12,473,282 to 12,563,147, reverse strand). Ensembl gene ENSG00000111266.
Subcellular location: Cytoplasm; Nucleus; Cytoplasmic vesicle
Subcellular location (Human Protein Atlas): Nucleoplasm
Pathways (Reactome):
Disease: Signaling by MAPK mutants; Suppression of autophagy
Signal Transduction: Negative regulation of MAPK pathway; RAF-independent MAPK1/3 activation
Gene Ontology:
Molecular function: JUN kinase binding; mitogen-activated protein kinase binding; mitogen-activated protein kinase p38 binding; phosphatase activity; phosphoprotein phosphatase activity; protein binding; protein carrier chaperone; MAP kinase tyrosine phosphatase activity; MAP kinase tyrosine/serine/threonine phosphatase activity; protein tyrosine/threonine phosphatase activity; protein serine/threonine phosphatase activity; protein tyrosine phosphatase activity
Biological process: dephosphorylation; negative regulation of MAPK cascade
Cellular component: cytoplasm; nucleoplasm; nucleus; cytosol; cytoplasmic vesicle
Genetic constraint (gnomAD): Loss-of-function variants: 21 observed, 60.22 expected, observed/expected ratio (o/e) 0.35, 90% interval 0.25 to 0.5. The upper end of that interval is the gene's LOEUF score, 0.5, which puts it in group 2 of 6, group 1 being the genes least tolerant of losing a copy. Missense variants: 726 observed, 862.1 expected, observed/expected ratio (o/e) 0.84, 90% interval 0.79 to 0.89. Synonymous variants: 320 observed, 339.74 expected, observed/expected ratio (o/e) 0.94, 90% interval 0.86 to 1.03.
Homologues: Orthologues: chimpanzee DUSP16 (99% identical), macaque DUSP16 (99% identical), dog DUSP16 (93% identical), guinea pig DUSP16 (93% identical), mouse Dusp16 (91% identical), rat Dusp16 (91% identical), pig DUSP16 (83% identical), tropical clawed frog dusp16 (67% identical), rabbit DUSP16 (52% identical), zebrafish dusp16 (50% identical). Paralogues in human: DUSP8 (44% identical), SSH2 (20% identical), SSH1 (19% identical), STYXL2 (18% identical), DUSP10 (18% identical), DUSP1 (17% identical), DUSP4 (17% identical), DUSP6 (17% identical), DUSP7 (16% identical), DUSP2 (16% identical), DUSP5 (16% identical), SSH3 (15% identical), and 19 more.
Diseases named in the same sentence as DUSP16 in open-access papers:
DUSP16 is named in the same sentence as 54 diseases in open-access papers, as found by Europe PMC text mining. Sharing a sentence is not in itself a finding about the gene and the disease. The quoted sentences say what the papers report.
Autoimmunity (2 papers, 2015 to 2019). The occurrence of an immune reaction against the organism's own cells or tissues. "In particular the specific role of DUSP16/MKP-7 in promoting autoimmunity make it a potential therapeutic target in a range of human disorders such as inflammatory bowel disease, rheumatoid arthritis and lupus." (PMID 30401534, 2019). "These include Tgfb3, which is important in Th17-mediated autoimmunity, Igf1r, which is highly expressed in T-ALL cells, Rsad2 (viperin), which is a regulator of viral infection, Cd24a, which is important in T-cell homeostasis and Dusp16, which is a negative regulator of JNK in T-cells." (PMID 25908851, 2015).
congenital obstructive hydrocephalus (2 papers, 2017 to 2019). "We further demonstrate that Dusp16 deficiency causes and combines congenital obstructive hydrocephalus and brain overgrowth." (PMID 29170629, 2017). "Here we report that the genetic inactivation of Dusp16 leads to congenital obstructive hydrocephalus and brain overgrowth." (PMID 29170629, 2017). "Embryos lacking DUSP16/MKP-7 exhibited congenital obstructive hydrocephalus together with brain overgrowth." (PMID 30401534, 2019). "Mouse mutants lacking a functional Dusp16 gene (Dusp16−/−) developed fully-penetrant congenital obstructive hydrocephalus together with brain overgrowth." (PMID 29170629, 2017).
Hydrocephalus (2 papers, 2017 to 2018). Hydrocephalus is an active distension of the ventricular system of the brain resulting from inadequate passage of CSF from its point of production within the cerebral ventricles to its point of absorption into the systemic circulation. "In conclusion, these findings indicate that the hydrocephalus observed in the Dusp16-deficient embryos was caused by aqueductal stenosis." (PMID 29170629, 2017). "In contrast, the occlusion of the midbrain aqueduct, preceding ventricular enlargement, strongly suggests that this is the cause of the hydrocephalus in Dusp16−/− mutants." (PMID 29170629, 2017). "To better understand the role of Dusp16 in neurogenesis and how aberrations in this process may cause hydrocephalus, we analyzed proliferation and differentiation of neural progenitors in the dorsal midbrain." (PMID 29170629, 2017). "Thus our data support obstruction of the midbrain aqueduct by over-proliferation of neural progenitors as the proximal cause of hydrocephalus in Dusp16−/− mutants." (PMID 29170629, 2017). "Similarly, the SCO was formed and produced RF, leading us to conclude that the overproliferation of neural progenitor cells we observed causes the hydrocephalus in Dusp16−/− mutants." (PMID 29170629, 2017). "Taken together, DUSP16 is a promising candidate gene for a broad spectrum of disorders combining hydrocephalus, brain overgrowth and abnormal MAPK signaling." (PMID 29170629, 2017). "The particular combination of hydrocephalus, brain overgrowth and abnormal MAPKs signaling, found in Dusp16−/− mutants, recapitulates aspects of different neurodevelopmental disorders." (PMID 29170629, 2017). "Lack of Dusp16 expression in the CP and the normal morphology of this structure, suggest that CSF overproduction is not the cause of hydrocephalus in Dusp16−/− mutants." (PMID 29170629, 2017). "Moreover, the overall morphology of the CP at E14.5 was normal in Dusp16−/− mutants, thereby suggesting that overproduction of CSF is unlikely to have caused the observed hydrocephalus." (PMID 29170629, 2017). "Moreover our results suggest that a lack of functional Dusp16 could play a central role in the molecular mechanisms linking brain overgrowth and hydrocephalus." (PMID 29170629, 2017).
osteosarcoma (2 papers, 2021 to 2022). A usually aggressive malignant bone-forming mesenchymal neoplasm, predominantly affecting adolescents and young adults. "Conversely, in osteosarcoma, it has been demonstrated to promote cell proliferation, invasion and metastasis by targeting the phosphatase DUSP16." (PMID 36396626, 2022).
ovarian carcinoma (2 papers, 2010 to 2022). A malignant neoplasm originating from the surface ovarian epithelium. "Methylation-specific PCR analysis of human breast and ovarian carcinoma cell lines and malignant melanoma cell lines revealed no detectable methylation in the DUSP16 CpG island, despite reproducible methylation in BL cell lines (data not shown)." (PMID 20551953, 2010).
amyloid (1 paper, 2025). "Besides, DUSP16 inhibition did not appear to impact Aβ deposition in either the 3xTg or SAMP8 mice, suggesting that the association between DUSP16 SNPs and MCI‐to‐AD conversion risk may be relevant to the impact of DUSP16 on hippocampal neurogenesis rather than its role in amyloid pathology." (PMID 39434411, 2025).
breast carcinoma (1 paper, 2021). "We have analyzed the association of DUSP16 with patient survival in two cohorts of cancer patients, a small cohort of HNSCC patients and a cohort of 113 breast cancer patients, and found that high DUSP16 levels in tumors were associated with significantly lower patient survival." (PMID 33863904, 2021). "To substantiate the role of DUSP16 in the regulation of cancer cell sensitivity to platinum-based chemotherapy, we examined a cohort of breast cancer patients who were treated with platinum-based drugs including cisplatin, carboplatin, and lobaplatin after surgery." (PMID 33863904, 2021). "In this study, we find that dual-specificity phosphatase 16 (DUSP16) regulates resistance to chemotherapy in nasopharyngeal carcinoma, colorectal cancer, gastric and breast cancer." (PMID 33863904, 2021). "This study examines the regulatory function of one DUSP member, DUSP16, in NPC, colorectal cancer, gastric cancer, and breast cancer in response to chemotherapy drug treatment." (PMID 33863904, 2021). "In addition, high DUSP16 expression was found to be associated with poorer disease-free survival in a cohort of HNSCC patients upon completion of chemoradiation therapy and in a cohort of breast cancer patients who received platinum-based chemotherapy after surgery." (PMID 33863904, 2021). "This study demonstrates that inducing the expression of DUSP16 may be a common strategy of various solid tumors, including NPC, CRC, gastric cancer, and breast cancer, to evade chemotherapy-induced cell apoptosis." (PMID 33863904, 2021). "To further elucidate the function of DUSP16 in cancer response to chemotherapy, we overexpressed this molecule in the NPC cell line HK-1, the CRC cell line DLD-1, and HCT116, the gastric cancer cell line Nugc3 as well as the breast cancer cell line MDA-MB-231." (PMID 33863904, 2021). "In summary, our study demonstrates that DUSP16 targets JNK and p38 to regulate the common cell death pathway, the BAX/caspase 3–caspase 9 pathway, in various types of solid tumors, including NPC, CRC, gastric cancer, and breast cancer to regulate chemotherapy-induced apoptosis." (PMID 33863904, 2021). "It is unclear why overexpression of DUSP16 resulted in a cross-talk between JNK/p38 and ERK only in NPC cells, but not in CRC, gastric cancer cells, or breast cancer cells." (PMID 33863904, 2021).
breast tumors (1 paper, 2021). "DUSP16 protein expression in these breast tumors was determined by immunohistochemistry." (PMID 33863904, 2021).
cognitive disorder (1 paper, 2025). A disease affects cognitive processes. "Nevertheless, the effect of DUSP16 on cognitive disorders by stimulating neural progenitor cell (NPC) differentiation in AD mice remains unclear." (PMID 39434411, 2025). "However, it remains uncertain whether the dephosphorylation function of DUSP16 is crucial for ameliorating cognitive disorders by affecting NPC differentiation in AD mice." (PMID 39434411, 2025).
dementia (1 paper, 2025). Loss of intellectual abilities interfering with an individual's social and occupational functions. "Here, the analysis of clinical SNPs data from ADNI revealed a potential association between DUSP16 and the risk of transitioning from MCI to AD dementia." (PMID 39434411, 2025).
gastric cancer (1 paper, 2021). A primary or metastatic malignant neoplasm involving the stomach. "First, we discovered that DUSP16 was differentially expressed in NPC, CRC, and gastric cancer cell lines." (PMID 33863904, 2021).
glioma (1 paper, 2016). A benign or malignant brain and spinal cord tumor that arises from glial cells (astrocytes, oligodendrocytes, ependymal cells). "RNAseq data from WT or IDH1 R132H-containing glioma xenografts E434 and E478 also do not point to an IDH-mutation associated difference in expression for DUSP16, PTPRG and PTPRT (WPJL, unpublished data)." (PMID 27586084, 2016).
head and neck cancer (1 paper, 2023). A primary or metastatic malignant neoplasm affecting the head and neck. "More specifically, DUSP16 has been shown to interact with MAPK14, which is involved in lymphangiogenesis, angiogenesis, and cell proliferation in head and neck cancer and cancer cells growth control." (PMID 37887710, 2023).
hepatocellular carcinoma (1 paper, 2022). A malignant tumor that arises from hepatocytes. "The only studied target gene whose expression was significantly downregulated after transfection with the miR-MAY-251 mimic was DUSP16, which is involved in cell viability and migration in hepatocellular carcinoma cell lines, and possibly improves viral replication." (PMID 35563619, 2022).
liver cancer (1 paper, 2022). An epithelial or non-epithelial malignant neoplasm that arises from the liver. "Accordingly, DUSP16 expression levels were found upregulated in liver cancer and positively correlated with the tumor cell proliferation index." (PMID 35936714, 2022).
liver fibrosis (1 paper, 2022). "Among all these analyzed DUSPs, DUSP3, DUSP8, DUSP12, DUSP14, DUSP16, DUSP22, and DUSP26 were significantly decreased in the liver of NASH patients with obvious hepatocyte ballooning, severe inflammatory infiltrate, and pattern of liver fibrosis compared with the normal individuals." (PMID 36209205, 2022).
marginal zone lymphoma (1 paper, 2010). A usually indolent mature B-cell lymphoma, arising from the marginal zone of lymphoid tissues. "Moreover, we did not detect methylation of DUSP16 in any cancer except BL, including analysis of a panel of NHL cell lines and clinical cases of DLBCL, FL, MCL and marginal zone lymphoma." (PMID 20551953, 2010).
myopia (1 paper, 2019). "Hypermethylation in the 5’UTR of Dual-Specificity Phosphatase 16 (DUSP16) was significantly associated with myopia in our study." (PMID 30858441, 2019).
non-Hodgkin lymphoma (1 paper, 2010). Distinct from Hodgkin lymphoma both morphologically and biologically, non-Hodgkin lymphoma (NHL) is characterized by the absence of Reed-Sternberg cells, can occur at any age, and usually presents as a localized or generalized lymphadenopathy associated with fever and weight loss. "In contrast to BL, the CpG island of DUSP16 is unmethylated in other non-Hodgkin's lymphomas (NHLs) and epithelial malignancies." (PMID 20551953, 2010).
pancreatic cancers (1 paper, 2015). "However, DUSP16 had similar expression levels in both pancreatic cancers and normal pancreatic samples (data not shown)." (PMID 26212664, 2015).
prostate carcinoma (1 paper, 2010). A carcinoma that arises from epithelial cells of the prostate gland. "A single previous study in prostate cancer has reported transcriptional downregulation of DUSP16 expression, but the mechanistic basis of downregulation was not established." (PMID 20551953, 2010).
RASopathies (1 paper, 2017). "A future, detailed analysis of the phenotype of these mutants outside of the CNS will provide necessary information, to follow up a potential role of DUSP16 in RASopathies." (PMID 29170629, 2017).
tumor (12 papers, 2010 to 2022). "In this respect, it is noteworthy that the DUSP16 gene is located on chromosome 12p, an area of frequent chromosomal loss in human tumours." (PMID 20551953, 2010). "DUSP16 loss is correlated with tumor progression, but its effect on OS development and the association of miR-769-5p/DUSP16 axis with JNK/p38 MAPK signaling in OS development remain unclear." (PMID 34663350, 2021). "Among Fourteen candidate target genes, DUSP16 was chosen for further study because it was involved in various tumors and plays a role in inhibiting tumor progression." (PMID 34663350, 2021). "DUSP16 IHC in tumor tissues further corroborated this conclusion." (PMID 34663350, 2021). "While people also found that DUSP16 had a role in pro-tumor development." (PMID 34088892, 2021). "On the other hand, the variable effects of JNK and p38 MAPKs on NB cell apoptosis endorse the possibility of a beneficial use of inhibitors of JNK- or p38-specific MKPs, such as DUSP1, DUSP8, DUSP10, or DUSP16, but only in NB cases in which the activity of JNKs or p38s favors tumor chemosensitivity." (PMID 30866462, 2019). "By contrast, 4 down-regulated genes are tumor suppressors (Lxn, Rassf4, Dusp16, Ifitm2)." (PMID 25229630, 2014). "DUSP16 may suppress the transformed phenotype of rodent fibroblasts expressing bcr-abl, consistent with a tumour suppressor function, although definitive evidence in support of this hypothesis is lacking." (PMID 20551953, 2010). "Although DUSP16 is commonly methylated in BL cell lines and endemic, sporadic and human immunodeficiency virus-associated BL, methylation was almost never detected in EBV-immortalised LCLs and the gene was abundantly expressed in these cells, implying that methylation is specific to neoplasia." (PMID 20551953, 2010). "In samples with high B7‐H3 expression, recurrent alterations included the deletion of short arm of chromosome 12 (12p), which contains tumor suppressors such as CDKN1B, ETV6, DUSP16, and miR‐613." (PMID 34562306, 2021). "Current studies indicate that DUSP2, DUSP4 and DUSP16 are involved in the co-adjustment between ERK1/2 and JNK, with these reports focusing on tumor cells and immune response." (PMID 25019380, 2014). "Future studies could be done to characterize DUSP16 expression levels and to correlate the status of JNK/p38 activation in the tumor tissues with the adjacent normal regions in chemosensitive and chemoresistant cancer patients." (PMID 33863904, 2021). "miR-27a-3p may also have an antitumor function in the development of HCC by targeting dual specificity phosphatase 16 (DUSP16) to decrease the viability and migration of tumor cells." (PMID 31572683, 2019). "However, DUSP8 and DUSP16 did not seem to play a major role in the regulation of basal JNK phosphorylation levels in other cancer cell lines, suggesting that different ROS-regulatable phosphatases might control the basal JNK activity in different types of tumour cells." (PMID 24115572, 2013).